GALNTL5 (polypeptide N-acetylgalactosaminyltransferase like 5)
Description:
Probable inactive glycosyltransferase required during spermatid development. May participate in protein loading into the acrosomes and accumulation of ubiquitin-proteasome systems around the head-tail coupling apparatus region.
Synonyms: GALNT15; GalNAc-T5L; GALNACT19
Tractability: Antibody: UniProt predicts a signal peptide or a membrane-spanning region. PROTAC: ubiquitination databases record sites on it.
Gene: Protein-coding gene on chromosome 7 (151,956,379 to 152,019,929, forward strand). Ensembl gene ENSG00000106648.
Subcellular location: Late endosome membrane
Pathways (Reactome):
Metabolism of proteins: O-linked glycosylation of mucins
Gene Ontology:
Molecular function: glycosyltransferase activity
Biological process: glycoprotein biosynthetic process; spermatid development
Cellular component: Golgi apparatus; late endosome membrane
Genetic constraint (gnomAD): Loss-of-function variants: 34 observed, 41.88 expected, observed/expected ratio (o/e) 0.81, 90% interval 0.62 to 1.08. The upper end of that interval is the gene's LOEUF score, 1.08, which puts it in group 4 of 6, group 1 being the genes least tolerant of losing a copy. Missense variants: 420 observed, 447.9 expected, observed/expected ratio (o/e) 0.94, 90% interval 0.87 to 1.02. Synonymous variants: 157 observed, 159.52 expected, observed/expected ratio (o/e) 0.98, 90% interval 0.86 to 1.12.
Homologues: Orthologues: chimpanzee GALNTL5 (93% identical), macaque GALNTL5 (93% identical), dog GALNTL5 (73% identical), rabbit GALNTL5 (70% identical), pig GALNTL5 (70% identical), guinea pig GALNTL5 (65% identical), rat Galntl5 (64% identical), mouse Galntl5 (63% identical), zebrafish galnt11 (49% identical), Drosophila melanogaster Pgant35A (41% identical), Caenorhabditis elegans gly-5 (38% identical), Caenorhabditis elegans gly-11 (38% identical), and 13 more. Paralogues in human: GALNT11 (53% identical), GALNT6 (37% identical), GALNT13 (37% identical), GALNT14 (37% identical), GALNT4 (37% identical), GALNT1 (37% identical), GALNT2 (37% identical), GALNT5 (37% identical), GALNT3 (36% identical), GALNTL6 (36% identical), GALNT15 (35% identical), GALNT12 (35% identical), and 7 more.
Diseases named in the same sentence as GALNTL5 in open-access papers:
GALNTL5 is named in the same sentence as 16 diseases in open-access papers, as found by Europe PMC text mining. Sharing a sentence is not in itself a finding about the gene and the disease. The quoted sentences say what the papers report.
asthenozoospermia (5 papers, 2016 to 2025). "Recent studies further suggest that Galntl5-deficient mice show male infertility owing to attenuated glycolytic enzymes (e.g., PGK2) required for motility and a patient diagnosed with asthenozoospermia had a mutation in the GALNTL5 gene." (PMID 27831554, 2016). "GALNTL5 was classified as CG, though our results confirm and re-inforce genotype/phenotype relation in the asthenozoospermia phenotype in men, therefore contributing to the upgrade of GALNTL5 as IG." (PMID 33809228, 2021). "Moreover, heterozygotic deletions of human GALNTL5 have been detected in patients diagnosed with asthenozoospermia (low sperm motility)." (PMID 39695134, 2024). "Furthermore, mutant mice heterozygous for Galntl5 were infertile, with impaired sperm motility and a high rate of morphological abnormalities resembling those seen in human asthenozoospermia." (PMID 39695134, 2024). "Similarly, the GALNTL5 and the KLK genes may be involved in the pathogenesis of asthenozoospermia." (PMID 33574797, 2020).
male infertility (4 papers, 2016 to 2025). The inability of the male to effect fertilization of an ovum after a specified period of unprotected intercourse. "The expression in the male reproductive tract and the physiological function of Gm55964 remain unclear, but the deletion of Gm55964 may cause more severe male infertility in Galntl5 mutant mice generated by Takasaki and his colleagues." (PMID 40962834, 2025).
breast carcinoma (2 papers, 2021). "SPTBN1 and GALNTL5 have also been implicated in breast cancer." (PMID 33672646, 2021). "The polypeptide N-acetylgalactosaminyltransferase-like protein 5 (GALNTL5) is involved in male fertility; however, its involvement in the development of breast cancer remains unclear." (PMID 35046993, 2021). "As GALNTL5, MLIP, HMCN2, LRRN4CL and DUOX2 were identified as cytotoxicity-associated genes, we next investigated their effects on therapeutic response by analyzing RNA-seq data and drug sensitivity of multiple breast cancer cell lines using Pearson coefficient analysis." (PMID 35046993, 2021). "(F-J) Survival analysis was performed for GALNTL5, MLIP, HMCN2, LRRN4CL and DUOX2 using log-rank test for RNA-seq data and the corresponding survival data from the TCGA cohort of patients with breast cancer." (PMID 35046993, 2021).
Infertility (2 papers, 2019 to 2025). "There is only one human mutation in a putative O-GalNAc-transferase, GALNTL5, which is associated with infertility." (PMID 31231650, 2019). "Herein, we demonstrate that knockout of Galntl5, encoding a sperm surface protein, causes impaired sperm binding with the UTJ and ZP, and null males have severe infertility." (PMID 40962834, 2025).
autism (1 paper, 2009). Persistent deficits in social interaction and communication and interaction as well as a markedly restricted repertoire of activity and interest as well as repetitive patterns of behavior. "Inspection of the remaining genes in the non-complex-autism group CNVs revealed three additional genes functioning in the same processes (B4GALT1, ARSA, and GALNTL5), for which Prioritizer had determined borderline significance (0.057<nominal p-value<0.074)." (PMID 19492091, 2009).
chronic kidney disease (1 paper, 2022). Impairment of the renal function secondary to chronic kidney damage persisting for three or more months. "Five variants associated also with chronic kidney disease progression mapped to genes with functional in-silico evidence (UMOD, SPATA7, GALNTL5, TPPP)." (PMID 35716955, 2022).
sterility (1 paper, 2025). "To understand why Galntl5 KO males show severe subfertility and sterility, we examined spermatogenesis and sperm motility." (PMID 40962834, 2025).
thyroid cancer (1 paper, 2021). "In summary, GALNTL5 is a testicular protein that strongly accumulates in a substantial fraction of endometrium and thyroid cancer samples." (PMID 33426787, 2021).
thyroid papillary carcinoma (1 paper, 2021). "We therefore confirmed the testicular expression of GALNTL5 using sections, and then, we employed tumor TMAs for endometrium (EM1021a, UT721) and thyroid papillary carcinoma (HThy‐Pap120CS‐01) for further analysis." (PMID 33426787, 2021).
cancer (3 papers, 2021 to 2024). A tumor composed of atypical neoplastic, often pleomorphic cells that invade other tissues. "Of interest were the associations with ANKRD30A, SPTBN1, and GALNTL5, as these genes have known and well-defined cancer associations." (PMID 33672646, 2021). "GALNTL5 interacts with RHOU, a Rho‐related GTP‐binding protein implicated in cancer cell migration (reviewed in Ref." (PMID 33426787, 2021). "This points to a potential role for GALNTL5 in cancer cell division and resistance to chemotherapy based on drugs that introduce DNA breaks, such as 5‐fluorouracil and cisplatin." (PMID 33426787, 2021). "Moreover, if it is possible to establish to specifically express GALNTL5 in cancer cells, GALNTL5 might serve as a novel anti-cancer drug." (PMID 39695134, 2024).
tumor (2 papers, 2021). "We performed RNA sequencing for 30 pairs of TNBC tissue and matched normal tissue from our hospital, and identified five pivotal genes (GALNTL5, MLIP, HMCN2, LRRN4CL, and DUOX2), which were correlated with associated with CD8+ T cell infiltration, tumor progression and therapeutic efficacy." (PMID 35046993, 2021).
adenocarcinoma (1 paper, 2021). A common cancer characterized by the presence of malignant glandular cells. "GeneChip profiling data for GALNTL5 show a classical CT gene pattern in an adenocarcinoma of the endometrium." (PMID 33426787, 2021).
GALNTL5 also shares sentences with these, for which no sentence is quoted: Azoospermia (1 paper); metastatic melanoma (1); metastatic tumors (1); teratozoospermia (1).